DCC (DCC netrin 1 receptor)
Diseases named in the same sentence as DCC in open-access papers (continued):
Sharing a sentence is not in itself a finding about the gene and the disease.
cancer (continued). "LATS2, MCC, DCC, RHOB, TRIM13, LIMD1, and GPC3 also strongly and positively regulated gene down-expression in cancer." (PMID 33580150, 2021). "Among the 58 cancers with DCC alterations, 17 tumors showed alterations in both DCC methylation and 18q LOH, 19 had 18q LOH alone, and 22 cancers exhibited DCC methylation alone." (PMID 26207151, 2015). "The gene expressions of netrin-1 dependence receptors, DCC and UNC5C, are frequently downregulated in many cancers." (PMID 26207151, 2015). "The SROs in these chromosome arms contains a number of protein coding genes, including well known critical cancer genes as BCL2 (18q22), DCC (18q21) and AURKA (20q13)." (PMID 20459617, 2010). "Expression of a 12 kb DCC mRNA was demonstrated in 14/34 (42%) of the cancers and in all five tumours with LOH at the DCC locus there was an additional 11 kb DCC mRNA." (PMID 8318422, 1993). "Four genes (DCC, EGFR, LRIG3, and RUNX1) mutated in GTKO-F0 pig No. 681 were previously found to be mutated in some human cancers." (PMID 40833781, 2025). "Significant differences between cancer and their surrounding non-cancerous tissues were observed in the methylation values of DCC (p = 0.003), EDNRB (p = 0.001), and ECAD (p = 0.043)." (PMID 38538728, 2024). "Besides this, rare and potentially pathogenic variants were identified in the DNA repair gene POLN and other cancer-related genes such as PPARG, CTC1, DCC and ALPK1." (PMID 36077770, 2022). "Using a set of mutations from 22 cancers we detect 151 putative cancer drivers, of which 79 are not listed in cancer resources and include recently validated cancer associated genes EPHA7, DCC netrin-1 receptor and zinc-finger protein ZNF479." (PMID 30670742, 2019). "In fact, reduced expression of DCC has been reported in several types of cancer (prostatic, colorectal and NB), unlike NEO1, which expression is not altered." (PMID 28038459, 2017). "The related tumour suppressor proteins Deleted in Colorectal Cancer (DCC) and neogenin are absent or weakly expressed in many cancers, whereas their insertion into cells suppresses oncogenic behaviour." (PMID 27716118, 2016). "While tissue slices expressed high levels of DCC and neogenin, the cancer-derived cell lines showed little or no intrinsic DCC expression." (PMID 27716118, 2016). "Overexpression of Neo was observed in multiple types of human cancer, especially in aggressive cancers; and unlike DCC and UNC5, Neo enhanced the proliferation and motility of GC cells in an Ntn1 independent manner." (PMID 25909166, 2015). "Among the cancers that were positive for DCC expression, only 2/34 cancers (6 %) demonstrated both methylation and LOH, 13/34 (38 %) cancers LOH alone, and 8/34 cancers (24 %) methylation alone (cancers showing both DCC methylation and 18q LOH vs. the others, P = 0.0048, Pearson’s chi-square test)." (PMID 26207151, 2015). "Among clinicopathological features, LOH ratio and CIN phenotype distribution differed significantly between cancers negative and positive for DCC alterations." (PMID 26207151, 2015). "Among autosomal genes, DCC (Deleted in Colon Cancer) was deleted in 50% of the cases, unlike in Caucasians where it was more frequently amplified than deleted." (PMID 22879877, 2012). "However, while Dex or TGFβ1 did not appreciably increase basal soft-agar colony formation over that observed in DCC alone, the GR antagonist, RU486, blocked soft-agar colony formation, demonstrating the GR-dependence of this cancer cell biology in 3D conditions." (PMID 32357907, 2020). "However, although the impact of mutating DCC in every cell of an organism has been investigated, somatic DCC mutant clones have not been assessed for cancer phenotypes in animal models." (PMID 21672235, 2011). "In addition to DCC, several other proteins function as Net receptors in vertebrates, suggesting that redundancy could explain the lack of cancer phenotypes in the DCC knockout mouse." (PMID 21672235, 2011).
cancer (continued). "First, unlike DCC where the mouse models have somewhat excluded its role in CRC (see the previous section), there have been no further studies on MCC that directly or indirectly suggest or dispute its role in cancer since its alteration in human CRC was first reported." (PMID 20707908, 2010).
psychiatric disorder (10 papers, 2010 to 2025). A disorder characterized by behavioral and/or psychological abnormalities, often accompanied by physical symptoms. "The psychiatric disorders are related to the mesocorticolimbic dopamine system which involves the Netrin-1/DCC signaling pathway." (PMID 38638604, 2024). "The NTN1/DCC signaling pathway, interacting with UNC5C, plays a crucial role in central nervous system axon guidance and has been associated with psychiatric disorders during adolescence in humans." (PMID 38540364, 2024).
genetic disorder (2 papers, 2019 to 2021). "The fourth shared gene, DCC (aromatic amino acid decarboxylase) is mutated in a rare genetic disorder and deficiency of this enzyme affects neurotransmitter production." (PMID 33608545, 2021).
adenocarcinoma (1 paper, 2011). A common cancer characterized by the presence of malignant glandular cells. "Although neither of these latter non-synonymous mutations have been previously reported, both are sited close to residues of interest: p.F1039S, mutated in adenocarcinoma; and p.Y1418, a critical residue phosphorylated by Fyn, and required for DCC function." (PMID 21750719, 2011).
bone disorder (1 paper, 2024). "Regarding the interaction between netrin-1 and DCC or UNC5 in bone disorders, netrin-1 is highly expressed in the synovial fluid of rheumatoid arthritis patients, and activation of the netrin-1/UNC5B axis has been shown to prevent bone destruction." (PMID 38628640, 2024). "Regarding their roles in bone disorders, UNC5B, as a downstream effector of netrin-1, has been shown to prevent bone destruction, and DCC has been reported to be expressed in a CD166-positive subpopulation of chondrocytes in human osteoarthritic cartilage." (PMID 38628640, 2024). "Thus, the specific modulation of DCC and UNC5B via netrin-1 may serve as a promising strategy to treat bone disorders." (PMID 38628640, 2024).
infection (1 paper, 2017). The state of being infected such as from the introduction of a foreign agent such as serum, vaccine, antigenic substance or organism. "On the other hand, DCC Netrin 1 Receptor (DCC), which mediates axon attraction of neuronal growth cones in the developing nervous system upon ligand binding, was subject to alt3 type of AS following the infection." (PMID 29116029, 2017).
DCC also shares sentences with these, for which no sentence is quoted: cervical carcinoma (3 papers); age-related macular degeneration (2); bipolar disorder (2); hematologic malignancies (2); intestinal cancer (2); multiple myeloma (2); neurodevelopmental disorder (2); neurologic disorders (2); osteoarthritis (2); Parkinson disease (2); prostate carcinoma (2); renal cell carcinoma (2); acute myeloid leukemia (1); adenocarcinoma in situ (1); adenosquamous carcinoma (1); Alzheimer disease (1); amyotrophic lateral sclerosis (1); appendiceal adenocarcinomas (1); Ataxia (1); autism (1); Barrett esophagus (1); bladder cancer (1); bladder transitional cell carcinoma (1); brain cancer (1); B‐cell lymphoma (1); cardiovascular diseases (1); cervical adenocarcinoma (1); colon adenocarcinoma (1); COVID-19 (1); cystadenoma (1).
A further 34 diseases each share a sentence with DCC in 1 paper.